GABARAP (GABA type A receptor-associated protein)
Description:
Ubiquitin-like modifier that plays a role in intracellular transport of GABA(A) receptors and its interaction with the cytoskeleton. Involved in autophagy: while LC3s are involved in elongation of the phagophore membrane, the GABARAP/GATE-16 subfamily is essential for a later stage in autophagosome maturation. Through its interaction with the reticulophagy receptor TEX264, participates in the remodeling of subdomains of the endoplasmic reticulum into autophagosomes upon nutrient stress, which then fuse with lysosomes for endoplasmic reticulum turnover. Also required for the local activation of the CUL3(KBTBD6/7) E3 ubiquitin ligase complex, regulating ubiquitination and degradation of TIAM1, a guanyl-nucleotide exchange factor (GEF) that activates RAC1 and downstream signal transduction. Thereby, regulates different biological processes including the organization of the cytoskeleton, cell migration and proliferation. Involved in apoptosis. Participates in selective ER-phagy through interaction with UBAC2, promoting recruitment of UBAC2-associated ER fragments to autophagosomes.
Synonyms: MM46; ATG8A; GABARAP-a
Tractability: Antibody: its Gene Ontology location is reachable by antibodies, with high confidence. PROTAC: ubiquitination databases record sites on it; its protein half-life has been measured.
Gene: Protein-coding gene on chromosome 17 (7,240,008 to 7,242,449, reverse strand). Ensembl gene ENSG00000170296.
Subcellular location: Cytoplasmic vesicle, autophagosome membrane; Endomembrane system; Cytoplasm, cytoskeleton; Golgi apparatus membrane; Cytoplasmic vesicle
Subcellular location (Human Protein Atlas): Vesicles
Pathways (Reactome):
Autophagy: Macroautophagy
Vesicle-mediated transport: TBC/RABGAPs
Gene Ontology:
Molecular function: beta-tubulin binding; GABA receptor binding; phosphatidylethanolamine binding; protein binding; protein sequestering activity; ubiquitin protein ligase binding; microtubule binding; phospholipid binding
Biological process: extrinsic apoptotic signaling pathway via death domain receptors; negative regulation of TORC1 signaling; positive regulation of lysosome organization; positive regulation of proteasomal ubiquitin-dependent protein catabolic process; positive regulation of protein K48-linked ubiquitination; regulation of Rac protein signal transduction; reticulophagy; autophagosome assembly; autophagosome maturation; cellular response to nitrogen starvation; chemical synaptic transmission; mitophagy; protein targeting; regulation of neurotransmitter receptor localization to postsynaptic specialization membrane
Cellular component: autophagosome; autophagosome membrane; axoneme; cytoplasmic vesicle; cytosol; endomembrane system; Golgi membrane; plasma membrane; actin cytoskeleton; cytoskeleton; GABA-ergic synapse; Golgi apparatus; lysosome; microtubule associated complex; smooth endoplasmic reticulum; sperm midpiece
Genetic constraint (gnomAD): Loss-of-function variants: 2 observed, 4.2 expected, observed/expected ratio (o/e) 0.48, 90% interval 0.19 to 1.44. That is too few expected variants to judge how well the gene tolerates losing a copy. Missense variants: 26 observed, 44.26 expected, observed/expected ratio (o/e) 0.59, 90% interval 0.43 to 0.81. Synonymous variants: 12 observed, 15.9 expected, observed/expected ratio (o/e) 0.75, 90% interval 0.48 to 1.22.
Homologues: Orthologues: chimpanzee GABARAP (100% identical), dog GABARAP (100% identical), macaque GABARAP (100% identical), mouse Gabarap (100% identical), pig GABARAP (100% identical), rabbit GABARAP (100% identical), Caenorhabditis elegans lgg-1 (83% identical), Drosophila melanogaster Atg8b (77% identical), guinea pig Phf23 (48% identical). Paralogues in human: GABARAPL1 (86% identical), GABARAPL2 (58% identical), MAP1LC3C (38% identical), MAP1LC3B (33% identical), MAP1LC3A (32% identical), MAP1LC3B2 (32% identical).
Diseases named in the same sentence as GABARAP in open-access papers:
GABARAP is named in the same sentence as 61 diseases in open-access papers, as found by Europe PMC text mining. Sharing a sentence is not in itself a finding about the gene and the disease. The quoted sentences say what the papers report.
breast cancer (13 papers, 2010 to 2025). A primary or metastatic malignant neoplasm involving the breast. "The present study assessed the possible value of γ-aminobutyric acid type A (GABAA) receptor-associated protein (GABARAP) as a therapeutic target in the metastasis of breast cancer." (PMID 33591943, 2021). "Evaluation of breast cancer patients and clinical data indicated that GABARAP was associated with the clinicopathology-related characteristics of malignancy and negatively correlated with the expression of MMP2 and MMP14." (PMID 33591943, 2021). "Similarly, a peptide mimicking the γ-aminobutyric acid type A (GABAA) receptor-associated protein (GABARAP) which interacts with TRPV1 has been proposed as a good candidate to promote TRPV1-associated suppression of breast cancer progression." (PMID 35565390, 2022). "Moreover, high GABARAP expression in tumor tissues was significantly associated with poor prognosis of patients with colorectal carcinoma and breast cancer." (PMID 36430876, 2022). "Results indicated that ATM and SEPP1 genes induced significant (p < 0.05) increased risk in BRCA-LumA patients than other type of breast cancer patients while GABARAP gene induced significant (p < 0.05) decreased risk in all BRCA patients, but IL7R in only BRCA-LumB patients." (PMID 34572798, 2021). "In other cancers, its role is context-dependent: GABARAP promotes tumor aggressiveness and poor survival in colorectal carcinoma, whereas in breast cancer it restrains epithelial-mesenchymal transition and invasion." (PMID 41346635, 2025). "In breast cancer datasets, the five most important mRNAs were GABARAP, PFDN5, RPL21, CFB, and PCED1A." (PMID 39495117, 2024). "For instance, in the context of breast cancer, decreased GABARAP levels have been observed to trigger EMT and facilitate tumor progression." (PMID 39664581, 2024). "We used a comprehensive research method based on clinical breast cancer specimens, cell and animal models to examine the expression and biological function of GABARAP." (PMID 33591943, 2021). "We also found that GABARAP mRNA negatively correlated with the clinical phase of breast cancer (P < 0.01)." (PMID 33591943, 2021). "In human breast cancer tissue samples, we first analyzed the relationship between GABARAP and the clinicopathology-related features of breast cancer." (PMID 33591943, 2021). "Our study performed an experimental validation at the cellular level on two GABARAP-high cell lines (UACC-812 and T47D) and one GABARAP-low breast cancer cell line (MDA-MB-453)." (PMID 33591943, 2021). "We also elucidated the mechanism of GABARAP in the inhibition of EMT in breast cancer cells, which is partially dependent on the AKT/mTOR signaling pathway." (PMID 33591943, 2021). "Conclusively, these data indicate that GABARAP suppresses the malignant behaviors of breast cancer likely via the AKT/mTOR pathway." (PMID 33591943, 2021). "According to the results, GABARAP mRNA expression in breast cancer tissues was much lower than normal tissue (P < 0.0001), and its expression in breast cancer subtypes was also lower (P < 0.0001)." (PMID 33591943, 2021). "To investigate the expression and role of GABARAP in breast cancer, we first analyzed GABARAP mRNA expression using RNA-seq data from the TCGA breast cancer cohort." (PMID 33591943, 2021). "Survival analyses revealed that breast cancer patients with low expression of GABARAP had a shorter survival time (P = 0.0047)." (PMID 33591943, 2021). "Compared to normal tissues, the expression of GABARAP in any subtype of breast cancer was lower, and gradually decreased with increasing clinical stage from stage I to III." (PMID 33591943, 2021). "Survival analysis revealed that the survival time of breast cancer patients with low expression of GABARAP was shorter." (PMID 33591943, 2021). "An inhibitor of the AKT/mTOR pathway, LY-294002, reversed the proliferation and invasion of breast cancer induced by GABARAP knockdown." (PMID 33591943, 2021).
breast cancer (continued). "The analyses of GABARAP mRNA expression in the breast cancer RNA sequence data in TCGA database strongly support the study of its potential role in breast cancer." (PMID 33591943, 2021). "As a negative regulator, GABARAP inhibits the activities of breast cancer via regulation of the EMT, which establishes the value and significance of GABARAP as an underlying target for therapies of the multi-level progression of the specific cancer." (PMID 33591943, 2021). "The results indicated that GABARAP also inhibited the EMT of breast cancer cells via the AKT/mTOR pathway in vivo." (PMID 33591943, 2021). "To evaluate the role GABARAP in the progress of breast cancer in vivo, we constructed a xenograft tumor model in nude mice using UACC-812 cell lines steadily transfected with vector control or GABARAP-shRNA." (PMID 33591943, 2021). "In summary, GABARAP has the potential to hinder the malignant progression of breast cancer and may serve as a promising target for diagnosis and therapeutic intervention." (PMID 39664581, 2024). "In contrast, GABARAP suppressed breast cancer progression through the AKT/mTOR signaling pathway; however, how GABARAP suppressed the signaling pathway remains unclear." (PMID 36430876, 2022). "Likewise, GABARAP was upregulated in tumor necrosis factor-α-resistant breast cancer cells, concomitant with several other autophagy-related genes." (PMID 36430876, 2022). "To examine whether GABARAP influenced the proliferation of breast cancer cell lines, we performed CCK8 assays to measure cell viability." (PMID 33591943, 2021). "These seemingly contradictory observations, GABARAP promoting tumorigenicity in normal (murine) cells, but inhibiting tumor growth in (human) breast cancer, correlates with the fact that autophagy as an essential cellular pathway can act oncogenic as well as tumor suppressive." (PMID 34502326, 2021). "Therefore, our results show that GABARAP represents a considerable target for breast cancer treatment and a new prognostic indicator." (PMID 33591943, 2021). "We investigated the expression and importance of GABARAP in breast cancer." (PMID 33591943, 2021). "The targeting of GABARAP may improve the certainty of diagnosis and treatment strategies for breast cancer." (PMID 33591943, 2021). "The results showed that the downregulation of GABARAP promoted the proliferation, invasion and metastasis of the different subtypes, and the overexpression of GABARAP inhibited the proliferation and metastasis of breast cancer cells." (PMID 33591943, 2021). "Our study first revealed the role of GABARAP in the invasion and metastasis of breast cancer." (PMID 33591943, 2021). "To examine whether GABARAP was also decreased in the cultured breast cancer cell lines, we performed Western blot analysis of eight breast cancer cell lines and non-transformed MCF-10A cells." (PMID 33591943, 2021). "In conclusion, we demonstrated that GABARAP suppressed the proliferation and invasion of breast cancer cells via regulation of the EMT in vitro and in vivo, and the mechanism may be related to regulation of the AKT/mTOR pathway." (PMID 33591943, 2021). "Moreover, tissue microarray experiments revealed a significant reduction in GABARAP protein expression in a high proportion of 93 breast cancers cases." (PMID 20197771, 2010). "GABARAP could enhance the precision of both diagnosis and treatment approaches for breast cancer." (PMID 39495117, 2024). "Therefore, we speculate that low GABARAP expression will affect the proliferation of tumor cells and plays a profound role in the occurrence and growth of breast cancer." (PMID 33591943, 2021). "Therefore, we examined whether GABARAP inhibited the EMT of breast cancer via regulation of the AKT/mTOR pathway." (PMID 33591943, 2021).
breast cancer (continued). "Consistent with the observations of the tumor cell lines and xenograft models, the distribution and intensity of GABARAP negatively correlated with MMP2 (P=0.0013) and MMP14 (P=0.019) in breast cancer tissue specimens." (PMID 33591943, 2021). "In contrast to NSCLC, GABARAP is also able to regulate epithelial-stromal transformation (EMT) in BC via the AKT/mTOR signaling pathway, thereby inhibiting the proliferation and invasion of breast cancer cells." (PMID 40900801, 2025). "Indeed, the expression of GABARAP and LC3 in breast cancer is significantly correlated with tumor malignancy and poor prognosis." (PMID 35054896, 2022). "We used Western blotting analysis to compare the expression levels of GABARAP in the breast cancer cell lines and non-transformed MCF-10A cells." (PMID 33591943, 2021). "Our team demonstrated, for the first time, that GABARAP inhibited EMT-related breast cancer tumor progression in a cell model, an animal model and human breast cancer tissue samples, and the mechanism may involve direct regulation of the AKT/mTOR pathway." (PMID 33591943, 2021). "The expression of MMP2 and MMP14 in human breast cancer samples was detected using IHC, and the results showed that GABARAP negatively correlated with MMP2 and MMP14, which indicates that GABARAP also inhibits invasion and metastasis in human breast cancer samples." (PMID 33591943, 2021). "The EMT plays a pivotal role in tumor metastasis, and we hypothesized that GABARAP affected the EMT process and inhibited breast cancer progression." (PMID 33591943, 2021). "Therefore, we examined whether GABARAP inhibited tumor cell migration and invasion via regulation of the EMT in breast cancer cells." (PMID 33591943, 2021). "However, whether GABARAP restrained the EMT and whether breast cancer development was involved in the autophagy process were not determined and will be a focus of our future research." (PMID 33591943, 2021).
colorectal cancer (7 papers, 2018 to 2025). A primary or metastatic malignant neoplasm that affects the colon or rectum. "A reduced GABARAP expression is associated with inferior differentiation of colorectal cancer and shorter overall survival, indicating its potential as a therapeutic target for colorectal cancer treatment." (PMID 39664581, 2024). "Some researchers have found that GABARAP is abnormally activated in colorectal cancer tissue, and its overexpression is positively correlated with the malignancy of the tumor, affecting the patient’s overall survival." (PMID 34636718, 2021). "GABARAP functions as a tumor suppressor in the development of colorectal cancer." (PMID 39664581, 2024). "Hitherto, only one research project has examined the prognostic significance of the GABARAP protein in colorectal cancer, thus showing that high levels of expression of this protein were connected to poor differentiation and to shortened overall survival in CRC patients." (PMID 30374741, 2018).
colon cancer (4 papers, 2015 to 2023). "Then, we collected seven pairs of colon cancer tissues and detected the expression of GABARAP and GABBR2 in the tissues by qRT-PCR." (PMID 38105184, 2023). "GABARAP, a mammalian Atg8 homolog, is upregulated following the pharmacological inhibition of p38ΜΑPK in a colon cancer cell line, resulting in autophagy and cell death." (PMID 32826872, 2020). "The p38 MAPK inhibitor SB202190 has been reported to impair the proliferation of human colon cancer cell lines in vitro and in mouse xenografts, which has been correlated with autophagy induction and increased expression of HER-3 and GABARAP." (PMID 25890501, 2015). "Taking together, our results indicate that p38 MAPK inhibition does not affect the expression of HER-3 and GABARAP, which are therefore unlikely to contribute to the reduced tumor growth observed in the PDXs from human colon tumors." (PMID 25890501, 2015).
multiple myeloma (4 papers, 2019 to 2026). "Moreover, loss of GABARAP compromises immunogenic cell death in multiple myeloma, reducing therapy efficacy, while in lung cancer, activation of a GABARAP-NIX axis induces selective mitophagy and radiosensitization." (PMID 41346635, 2025). "We then focus on hematological malignancies, especially multiple myeloma, where recent reports implicate the autophagy-related protein GABARAP in bortezomib-induced ICD." (PMID 41595126, 2026). "Previous research has shown that GABARAP interacts directly with CALR in vitro and it co-localizes (punctuate structure) and co-immunoprecipitates with CALR in the mouse neural precursor and neuroblastoma model N2a (Neuro 2A) cells, as well as in AMO1 multiple myeloma cells, respectively." (PMID 40650127, 2025). "Evidence also showed that the deletion of the GABARAP protein diminished the surface exposure of CALR during immunogenic cell death (ICD), subsequently reduced phagocytosis, disrupted the Golgi apparatus, and interrupted the autophagy machinery in multiple myeloma cells." (PMID 40650127, 2025).